CRP (C-reactive protein)
Diseases named in the same sentence as CRP in open-access papers (continued):
Sharing a sentence is not in itself a finding about the gene and the disease.
Pancytopenia (continued). "Laboratory examination showed pancytopenia (WBC 2370/mmc, Hb 10.5 g/dl, PLT 76.000/mmc), renal impairment (sCreat 3.7 mg/dl, eGFR CKD-EPI 19 ml/min), elevated C-reactive protein (CRP 12 mg/dl), and elevated ferritin (902 ng/ml)." (PMID 36329343, 2023). "Blood investigations revealed pancytopenia, elevated erythrocyte sedimentation rate (ESR) and C- reactive protein (CRP), and positive titers for anti-nuclear antibody (ANA) and anti-Po ribosomal P proteins (RPP) antibodies." (PMID 36447701, 2022). "Biochemical analysis revealed pancytopenia, raised erythrocyte sedimentation rate (ESR) and C-reactive protein (CRP), and mild microscopic proteinuria." (PMID 34422427, 2021). "Laboratory data revealed pancytopenia, elevated alkaline phosphatase (ALP), erythrocyte sedimentation rate (ESR), and C-reactive protein (CRP)." (PMID 34749829, 2021). "He received NSAIDs, sulfasalazine, methotrexate (MTX) in the treatment without significant effect and with the development of pancytopenia; at the same time, a persistent increase in the level of CRP was maintained." (PMID 37848930, 2023). "The condition worsened 3 days later and the patient complained of headache but no fever, and laboratory data revealed pancytopenia and markedly elevated CRP." (PMID 32601727, 2020). "Due to pancytopenia and a drug-induced rash, vancomycin was switched to teicoplanin on POD32, which was discontinued the following day, and inflammatory markers on blood testing demonstrated a marked improvement, with the C-reactive protein (CRP) level having decreased to 2.5 mg/dL." (PMID 40704247, 2025). "Complete blood count was suggestive of pancytopenia with hemoglobin of 10.8 g/dL, total white cell count 3.36 (1000/uL) (absolute neutrophil count 490 micro/L), platelets 19,000, serum albumin 3.1 g/dL, ESR elevated at 83 mm/hr, CRP elevated at 86.6 mg/L, and ferritin mildly elevated at 625 ng/mL." (PMID 38523896, 2024). "A patient with VL shows a number of clinical features such as fever, malaise, weight loss, and hepatosplenomegaly, as well as some nonspecific laboratory findings like pancytopenia, hypergammaglobulinemia, elevated C-reactive protein (CRP) level, and high erythrocyte sedimentation rate (ESR)." (PMID 27418985, 2016).
cerebral infarction (75 papers, 2007 to 2026). An ischemic condition of the brain, producing a persistent focal neurological deficit in the area of distribution of the cerebral arteries. "Although plasma C-reactive protein (CRP) is elevated in response to inflammation caused by brain infarction, the association of CRP with clinical outcomes after acute ischemic stroke remains uncertain." (PMID 27258004, 2016). "Accordingly, Hs-CRP can be as an independent risk factor for cerebral infarction to predict the severity of cerebral infarction and infarct size." (PMID 25888429, 2015). "All the variations of the variables considered in this study seem to be attributable to 2 main changes, namely those concerning GOT and CRP, which in turn were the only variables independently associated with cerebral infarct size." (PMID 24903748, 2014). "However, those with a history of cerebral infarction and with a CRP level of ≥ 0.15 mg/dL had an increased mortality risk in the higher Hb categories of ≥ 12 g/dL." (PMID 39932639, 2025). "Higher CRP concentrations were significantly associated with larger brain infarcts." (PMID 39970158, 2025). "Therefore, plasma CRP levels are elevated owing to underlying vascular lesions as well as inflammation caused by brain infarction in patients with acute ischemic stroke." (PMID 27258004, 2016). "In obese patients, elevated levels of inflammatory markers such as C-reactive protein (CRP), IL6, TNFα, MCP1, and ICAM-1 have been associated with higher risks of cerebral infarction." (PMID 39624169, 2024). "In non-parametric analysis, CSF cell count (p = 0.03), GCS on admission (p = 0.02), age (p = 0.005), a complication of cerebral infarction (p < 0.001), and CRP (p = 0.007) had relationships with poor prognosis." (PMID 38707085, 2024). "Combined with inflammatory factors CRP and IL-6, it has important clinical value in diagnosing the severity and prognosis of cerebral infarction and is expected to be a biomarker for diagnosing and predicting the progression and prognosis of ACI." (PMID 37119591, 2023). "In pathological conditions, however, e.g., cerebral infarction, CRP level has been found to increase during the first three hours in brain, reaching the peak at 48–72 h, and decreases after pathological process recovers." (PMID 35659067, 2022). "Clinical studies have confirmed that changes in the CRP level are helpful to understand the disease progression and occurrence of cerebral infarction in TIA." (PMID 35399851, 2022). "The authors found that advanced age, high SOFA scores, previous cerebral infarction, elevated plasma CRP levels (>0.6 mg/dL), and high lactate dehydrogenase activity (>245 U/L) increased the risk of death." (PMID 35766706, 2022). "Univariate analysis revealed that DAR, WFNS grade, Hunt–Hess grade, delayed cerebral infarction (DCI), age, neutrophil-to-lymphocyte ratio (NLR), and CRP/albumin ratio (CAR) were associated with unfavorable outcomes." (PMID 36552160, 2022). "Cross-sectional studies have found that TNF-α, IL-1, IL-6 and CRP are associated with WMH, silent brain infarcts, lower eGFR levels and a higher UACR." (PMID 34072230, 2021). "It has been reported that HD patients show a higher rate of silent cerebral infarctions, which is reflected by elevated CRP." (PMID 31830923, 2019). "The systematic review and meta-analysis will assess the effect of acupuncture on the expression of inflammatory factors TNF-α, IL-6, IL-1 and CRP in cerebral infarction with up-to-date clinical evidence." (PMID 31192907, 2019). "Brain infarction volume, neurological score, spatial memory, serum lipid profiles, and C-reactive protein together with the brain oxidative stress status were assessed." (PMID 29457029, 2017). "In contrast, the area of cerebral infarction in patients with small artery disease was relatively smaller, with less inflammation; therefore, the hs-CRP level was lower." (PMID 25680111, 2015).
cerebral infarction (continued). "In this study, the patient showed a past history of obstruction; cerebral infarction was a secondary presentation and C-reactive protein level was mildly elevated." (PMID 25954312, 2015). "The inhibition of CRP has been considered as a treatment for myocardial and cerebral infarcts due to the complementary role that CRP plays in enhancing ischemic necrosis, but has only been tested in animals to date." (PMID 24794233, 2014). "CRP can exacerbate ischemic necrosis in a complement-dependent fashion and that CRP inhibition can be a safe and effective therapy for myocardial and cerebral infarcts; this has only been demonstrated in animal models." (PMID 21430962, 2011). "We studied three cut-off values for CRP and produced age-specific receiver operating characteristics (ROC) curves, using patients with acute coronary or cerebral infarction as controls." (PMID 18706087, 2008). "In addition to conventional vascular risk factors, serum biomarkers such as interleukin-6 (IL-6) and C-reactive protein (CRP) have been studied about silent brain infarction (SCI), reflecting systemic inflammation." (PMID 40917659, 2025). "MIA factors were defined in patients with: low geriatric nutritional risk index (< 92) as “malnourished”; greater high-sensitivity C-reactive protein levels (≥ 0.1 mg/dL) as “inflamed”; a history of coronary artery revascularization, lacunar or atherothrombotic brain infarction as “atherosclerotic”." (PMID 39446306, 2025). "Abnormal blood test results, including elevated WBC and CRP levels on admission, may have contributed to the cerebral infarction." (PMID 39364502, 2024). "Plasma CRP levels were only marginally associated with the presence of brain infarcts in the two groups, though the infarct subtype was not specified." (PMID 37685924, 2023). "Therefore, CRP has also been explored as a potential marker for the diagnosis of Trousseau syndrome in patients with cerebral infarction." (PMID 36065806, 2022). "At the same time, a previous study highlighted that if patients with cerebral infarction are higher in age, have a history of smoking, and have elevated CRP, clinicians should be alert as to whether the patients have an underlying malignancy." (PMID 36065806, 2022). "Thus, the possibility of finding a silent brain infarction increases significantly by measurement of PC-Acro, IL-6 and CRP in plasma together with 3-HPMA in urine, and contributes to maintenance of quality of life (QOL) of the elderly." (PMID 32824278, 2020). "In addition, the elevation of serum C-reactive protein also showed positive correlation with brain infarct volume." (PMID 29457029, 2017). "Thus, the rationale for targeting CRP is based upon the ability of human CRP to increase myocardial and cerebral infarct size in rats subjected to coronary or cerebral artery ligation, respectively." (PMID 19690638, 2007). "We found that measurement of PC-Acro together with IL-6 and CRP makes it possible to identify SBI with high sensitivity and specificity and can decrease the number of people with cerebral infarction as mentioned in the introduction." (PMID 36830667, 2023). "The higher the serum CRP level, the more likely the patient is to develop a cerebral infarction The results displayed that Huoxue Tongluo prescription effectively downregulated MMP-9, Hcy, and CRP levels." (PMID 35399851, 2022). "Thirdly, our study did not incorporate inflammatory markers such as CRP, which limits investigation into the influence of inflammatory response on the progression of cerebral infarction." (PMID 39723423, 2024). "CRP levels have been shown to be elevated in patients with cancer and cerebral infarction compared with patients with cerebral infarction but without cancer." (PMID 36065806, 2022). "Hs-CRP is an excellent marker of general inflammatory response, but it does not appear to be a specific marker of cerebral infarction." (PMID 35085298, 2022).
cerebral infarction (continued). "Furthermore, small brain infarction without obvious symptoms was identified with approximately 84% sensitivity and specificity by measuring PC-Acro together with interleuklin-6 (IL-6) and C-reactive protein (CRP) in plasma in clinical studies." (PMID 36830667, 2023). "Other factors, including sex, race, cerebral infarction, SBP, oxygen saturation (SpO2), lymphocytes, CRP, and medications, were found not to be significantly associated with 30-day or 1-year mortality (p > 0.05)." (PMID 38249742, 2023).
fungal infections (75 papers, 2006 to 2026). "The multivariate analysis revealed that postoperative CRP is an independent risk factor for predicting multidrug-resistant bacterial and fungal infections." (PMID 39669267, 2024). "The AUC of CRP for discriminating viral from bacterial/fungal infections was 0.64 (95% CI, 0.58–0.69)." (PMID 41544183, 2026). "C reactive protein is an acute-phase protein that increased in any inflammatory condition and in patients with invasive fungal infections." (PMID 35752831, 2022). "The results showed that the serum albumin levels and lymphocyte counts were significantly lowered, and the CRP levels were significantly raised after fungal infection." (PMID 36237437, 2022). "One study shows, for fungal infections, a combination of CRP 100–300 mg/L and PCT < 0.5 μg/L offers positive predictive values of 73%, and negative predictive values of 89% in immunocompromised patients." (PMID 34996910, 2022). "The most discriminatory parameters for secondary bacterial/fungal infections (p-value, ROC-AUC, 95% CI) were CRP (p = 0.0005, 0.77, 0.65–0.88), IL-10 (p < 0.0001, 0.88, 0.73–0.94), and PCT (p = 0.0008, 0.76, 0.65–0.88)." (PMID 36275812, 2022). "The immune negative feedback regulation in response to IFI occurs because not only GLB protects humans from fungal infections, but also CRP as a routine biomarker for clinical infections rises during infection." (PMID 35794923, 2022). "In contrast, C-reactive protein and procalcitonin levels showed a significant positive correlation with fungal infection." (PMID 36237437, 2022). "G test and GM test of patients were positive, suggesting fungal infection accompanied by the increase of inflammatory markers such as CRP and PCT." (PMID 33555444, 2021). "This specific feature of presepsin makes it a superior biomarker to procalcitonin or C-Reactive Protein, which have significantly longer kinetics in bacterial or fungal infections." (PMID 33374939, 2020). "In this study, we evaluated CRP and IL-8 as biomarkers for bacterial and fungal infection in FN along with their usefulness in FN during chemoradiation-induced oropharyngeal mucositis." (PMID 32076032, 2020). "In our series, all patients had fever, cough and high CRP concentrations, which were similar to bacterial and fungal infection." (PMID 30736822, 2019). "In fungal infection, CRP levels are generally higher than PCT." (PMID 41590467, 2026). "C-reactive protein (CRP) is an acute-phase reactant produced by the liver in response to cytokines such as IL-6, IL-1, and TNFα, elevating in various inflammatory states, including bacterial, viral, and fungal infections." (PMID 39858517, 2025). "However, upon further review, we noted despite negative serum Bandavirus dabieense result and the use of antibiotics, CRP levels continued to rise rapidly after the first EE, suggesting a fungal infection." (PMID 39856548, 2025). "A previous study found increased CRP levels in children with fungal infection." (PMID 40376457, 2025). "Some abnormal blood biochemical tests result in the early stage of hospitalization, such as the increase of CRP, transaminase, and ferritin, and the decrease of hemoglobin could be related to the status of fungal infection." (PMID 40625894, 2024). "Increased WBC and CRP were associated with gram negative infection, while decreased platelet and glucose levels were associated with fungal infection." (PMID 35012001, 2022). "In addition, APACHE II score, EPIC score, modified Marshall score, CRP, WBC, Ca, Lac, amylase, fungal infection, bleeding, ACS, and organ failure were also the risk factors of death for SAP." (PMID 35126508, 2022). "Increased WBC and CRP were associated with gram negative infection, while decreased platelet and glucose level were associated with fungal infection." (PMID 35012001, 2022). "Additionally, the white blood cell (WBC) counts and C-reactive protein (CRP) levels are increased in fungal infections." (PMID 33750330, 2021).
fungal infections (continued). "This study confirmed the relative specificity of presepsin for bacterial infection and the authors that elevated CRP in conjunction with presepsin within the normal reference range was in favor of fungal infection in this group of immunocompromized individuals." (PMID 34150378, 2021). "The high level of CRP was probably indicative of a bacterial or fungal infection." (PMID 26185693, 2015). "Interestingly, two small sample studies recently showed that substantially elevated CRP combined with low PCT in immunocompromised adult patients may indicate systemic fungal infection." (PMID 35740137, 2022). "Conventional inflammatory markers, such as C-reactive protein (CRP), can aid suspicion but lack specificity for fungal infections." (PMID 39797289, 2025). "Patients with higher LCR demonstrated a lower prevalence of smoking, Gram-positive bacterial and fungal infections, lower levels of WBC, Neu, CRP, Tbil, AST, glucose, creatinine, BUN, uric acid, and lactate." (PMID 39347502, 2024). "C-reactive protein (CRP) is a standard immunochemical marker being measured to diagnose some types of bacterial and fungal infections, recognize inflammatory and some autoimmune disorders, and cardiovascular diseases." (PMID 35624645, 2022). "Forty-nine patients had bacterial and fungal infections, with a median body temperature of 36.8 (36.7–37.6) °C (the mean value is 37.08 ± 0.63 °C), median PCT of 0.26 (0.08–1.10) ng/ml, and median CRP of 19.10 (10.04–39.15)." (PMID 36319826, 2022). "Studies looking into the value of CRP and PCT in immunocompetent patients with fungal infections are scarce." (PMID 34996910, 2022). "With general bacterial infectious diseases, serum CRP and PCT levels will be significantly increased, and in fungal infectious diseases, they are rarely increased." (PMID 34234782, 2021). "Patients with isolated fungal infections were more likely to be male, possess tumors, have a recent surgery (within 2 weeks) and have lower levels of lymphocytes, PCT, and CRP." (PMID 33194796, 2020). "Furthermore, while presepsin demonstrates better specificity than CRP and is often comparable or superior to PCT, its performance in fungal infections appears limited unless used in conjunction with other markers such as 1,3-β-D-glucan." (PMID 40804836, 2025). "Considering that the infection was worsening and C-reactive protein (CRP) levels were continuously elevated, imipenem and cilastatin sodium were administered to fight bacterial infections, and micafungin was continued to prevent fungal infections." (PMID 39040893, 2024). "In addition, this study found that serum albumin as well as lymphocyte and monocyte counts were significantly negatively correlated with fungal infection, whereas the CRP and PCT values showed a significant positive correlation with fungal infection." (PMID 36237437, 2022). "We found that CRP and WBC count were not ideal diagnostic tools for identifying C. difficile infections or other viral and fungal infections in IBD patients." (PMID 36553115, 2022). "In the present study, CRP level increased in 89.7% of cases while PCT increased in 51.3% consistent with the study by Gunasekaran and coworkers that reported “PCT was elevated in nearly half of documented viral and fungal infections” in pediatric oncology." (PMID 35752831, 2022). "Of note, this was an open-label platform trial (not the highest quality standard) and patients were only eligible if CRP was ≥75 mg/L and if there was no uncontrolled bacterial or fungal infection." (PMID 35449467, 2022). "After excluding 129 patients without PCT or CRP, 39 patients with mycobacterial/fungal infections were detected, 423 patients with no pathogens detected, with 209 patients included in the current analysis." (PMID 34583675, 2021). "Classical biomarkers, such as C-reactive protein and leukocyte count, were not able to predict relevant bacterial or fungal infections." (PMID 27503068, 2016).